SOX6 (SRY-box transcription factor 6)
Description:
Transcription factor that plays a key role in several developmental processes, including neurogenesis, chondrocytes differentiation and cartilage formation (Probable). Specifically binds the 5'-AACAAT-3' DNA motif present in enhancers and super-enhancers and promotes expression of genes important for chondrogenesis. Required for overt chondrogenesis when condensed prechondrocytes differentiate into early stage chondrocytes: SOX5 and SOX6 cooperatively bind with SOX9 on active enhancers and super-enhancers associated with cartilage-specific genes, and thereby potentiate SOX9's ability to transactivate. Not involved in precartilaginous condensation, the first step in chondrogenesis, during which skeletal progenitors differentiate into prechondrocytes. Together with SOX5, required to form and maintain a pool of highly proliferating chondroblasts between epiphyses and metaphyses, to form columnar chondroblasts, delay chondrocyte prehypertrophy but promote hypertrophy, and to delay terminal differentiation of chondrocytes on contact with ossification fronts. Binds to the proximal promoter region of the myelin protein MPZ gene, and is thereby involved in the differentiation of oligodendroglia in the developing spinal tube. Binds to the gene promoter of MBP and acts as a transcriptional repressor (By similarity).
Synonyms: HSSOX6; SOXD; TOLCAS
Tractability: PROTAC: UniProt records ubiquitination sites on it; ubiquitination databases record sites on it.
Gene: Protein-coding gene on chromosome 11 (15,966,449 to 16,739,591, reverse strand). Ensembl gene ENSG00000110693.
Subcellular location: Nucleus; Cytoplasm
Subcellular location (Human Protein Atlas): Nucleoplasm
Pathways (Reactome):
Signal Transduction: Deactivation of the beta-catenin transactivating complex
Gene Ontology:
Molecular function: DNA-binding transcription factor activity; protein binding; protein homodimerization activity; transcription cis-regulatory region binding; DNA binding; DNA-binding transcription factor activity, RNA polymerase II-specific; DNA-binding transcription repressor activity; RNA polymerase II cis-regulatory region sequence-specific DNA binding
Biological process: brain development; cellular response to transforming growth factor beta stimulus; negative regulation of cardiac muscle cell differentiation; positive regulation of cartilage development; positive regulation of chondrocyte differentiation; positive regulation of mesenchymal stem cell differentiation; cartilage condensation; cartilage development; cell fate commitment; central nervous system development; chondrocyte differentiation; muscle organ development; regulation of DNA-templated transcription; regulation of transcription by RNA polymerase II; spinal cord oligodendrocyte cell differentiation; negative regulation of DNA-templated transcription
Cellular component: nucleoplasm; nucleus; chromatin; cytoplasm
Genetic constraint (gnomAD): Loss-of-function variants: 9 observed, 95.07 expected, observed/expected ratio (o/e) 0.0947, 90% interval 0.056 to 0.17. The upper end of that interval is the gene's LOEUF score, 0.17, which puts it in group 1 of 6, group 1 being the genes least tolerant of losing a copy. Missense variants: 768 observed, 1,062 expected, observed/expected ratio (o/e) 0.72, 90% interval 0.68 to 0.77. Synonymous variants: 352 observed, 382.61 expected, observed/expected ratio (o/e) 0.92, 90% interval 0.84 to 1.
Gene-disease validity (ClinGen):
ClinGen rates the evidence that SOX6 causes each of these diseases.
complex neurodevelopmental disorder (autosomal dominant): Definitive. A disorder that involves more than one phenotype associated with the central nervous system, including but not limited to intellectual disability, autism, and seizures (epilepsy).
Homologues: Orthologues: chimpanzee SOX6 (99% identical), macaque SOX6 (99% identical), pig SOX6 (99% identical), rabbit SOX6 (99% identical), guinea pig SOX6 (98% identical), mouse Sox6 (97% identical), rat Sox6 (97% identical), tropical clawed frog sox6 (80% identical), zebrafish sox6 (74% identical), Drosophila melanogaster Sox102F (22% identical), Caenorhabditis elegans egl-13 (19% identical), Drosophila melanogaster Sox14 (15% identical), and 1 more. Paralogues in human: SOX5 (56% identical), SOX13 (32% identical), SOX30 (13% identical), SOX9 (12% identical), CFAP65 (11% identical), SOX2 (10% identical), SOX8 (10% identical), SOX3 (10% identical), SOX4 (10% identical), SOX11 (10% identical), SOX17 (9% identical), SOX1 (9% identical), and 8 more.
Diseases named in the same sentence as SOX6 in open-access papers:
SOX6 is named in the same sentence as 120 diseases in open-access papers, as found by Europe PMC text mining. Sharing a sentence is not in itself a finding about the gene and the disease. The quoted sentences say what the papers report.
glioma (20 papers, 2007 to 2025). A benign or malignant brain and spinal cord tumor that arises from glial cells (astrocytes, oligodendrocytes, ependymal cells). "Our research suggests that when applied alone or in combination with irradiation, PACAP38 can upregulate the expression of SOX6 by acetylating histones and suppressing the Wnt-β-catenin signaling to exert inhibitory impact on glioma and breast cancer cells." (PMID 39619607, 2024). "KM analysis of the GEPIA platform based on the TCGA database showed that those with higher levels of SOX6 mRNA among glioma patients had better OS and RFS than those with lower levels of SOX6 mRNA." (PMID 39619607, 2024). "It has been demonstrated that SOX6 expression is positively correlated with SOX21 expression in glioma patients." (PMID 38132438, 2023). "Owing to its predominant expression in neurodevelopment, SOX6 represents a putative tumor-specific antigen in glioma; treatment of mice with a SOX6-DNA vaccination had protective and anti-tumorigenic effects on tumor bearing mice." (PMID 34012965, 2021). "It has been reported that circ_PTN can affect the function of glioma cells through targeting miR-122/SOX6 or miR-432-5p/RAB10 axis." (PMID 34853725, 2021). "While SOX6 is expressed in gliomas and medulloblastomas, it shows differential expression levels depending on tumor subtype, with lower levels found in GBM and higher levels present in oligodendrogliomas." (PMID 34012965, 2021). "As previously reported, Circ_PTN performed as sponge of miR-122, and activated SOX6 expression in glioma cells." (PMID 32388501, 2020). "For example, Chen and his colleagues demonstrated that circ_PTN acted as an oncogenene in the tumorigenesis of glioma through targeting miR-122 to regulate SOX6 expression." (PMID 32863771, 2020). "Functional analyses of Sox6 in adult mouse NSPCs, and especially in human gliomas and glioma-initiating cells, will pave the way for evaluating Sox6 as a therapeutic target for many brain diseases." (PMID 24066135, 2013). "Human leukocyte antigen-A2- and A24-restricted CTL peptides derived from SOX6 have been identified, and glioma patient lymphocytes stimulated with these peptides are capable of inducing glioma-specific CTLs." (PMID 23762610, 2013). "We previously reported that SOX6 is highly expressed in human gliomas and that Macrophage migration inhibitory factor (MIF) supports the proliferation and/or survival of murine NSPCs in vitro." (PMID 24066135, 2013). "Both of them are overexpressed in gliomas, and while SOX6 was recently proposed as a possible important factor in obesity-related insulin resistance, SOX5 overexpression and amplification has been observed in human testicular seminoma." (PMID 18510758, 2008). "SOX6 protein has multiple helper epitopes, which can induce anti-tumor activity in glioma." (PMID 39889187, 2025). "Other SHH-1A associated genes were the neuroendocrine-specific tumor genes SST and SCG2; ARPP21, encoding an RNA-binding protein found in glioma, and SOX6, a tumor marker expressed by not fully differentiated neuronal and glial cells." (PMID 35501487, 2022). "Furthermore, SOX6 is expressed at very low levels in the adult brain, but higher in fetal brain and gliomas." (PMID 31839753, 2019). "SOX6 was found to specifically expressed either in foetal brain or gliomas, but faintly in the adult brain, which again indicates that it might have a role in transformation by repressing various tumour-suppressive targets like the ARRB1 locus." (PMID 27871300, 2016). "We have identified human glioma antigen SOX6, which is expressed in glioma stem-like cells." (PMID 23755373, 2013). "Sox6-DNA vaccination was able to inhibit growth of murine glioma in a therapeutic setting." (PMID 23755373, 2013).
glioma (continued). "However, the number of GSC-associated proteins' peptide epitopes known to elicit T-cell responses is rather limited, and sox6 is the first protein expressed in glioma stem cells whose peptides are potentially immunogenic in patients with HLA-A∗24 or -A∗02 positive glioma." (PMID 25126583, 2014). "Thus, it may be important to analyze the detailed function of Sox6 in gliomas and glioma-initiating cells in the future." (PMID 24066135, 2013). "Several authors have already applied SEREX to glioma, and some antigens, including glioma-expressed antigen 2 (GLEA2), PHD finger protein 3 (PHF3), and SRY-box 6 (SOX6) have been identified." (PMID 23050879, 2012). "MAGE-1 and SOX6 are both CT antigens and have been observed in gliomas but not in normal brain tissues." (PMID 23762610, 2013). "SOX6 was identified using SEREX (serological identification of antigens by recombinant expression cloning) and may be a candidate antigen that targets GSCs because of its specific expression in glioma and GSCs." (PMID 23762610, 2013).
cervical cancer (14 papers, 2021 to 2025). A primary or metastatic malignant neoplasm involving the cervix. "In hematologic malignancies cervical cancer and multiple myeloma SOX6 demonstrates tumor-suppressive properties by inhibiting proliferation, inducing cellular senescence or apoptosis, and regulating critical pathways including TGFβ2-Smad2/3 and LIN28B-MYC." (PMID 40866912, 2025). "This study uncovers that the MAP4K4/WT1–ATF2–TGFβ2 axis mediates SOX6‐induced cellular senescence, which is a promising therapeutic target in improving the chemosensitivity of cervical cancer." (PMID 38383842, 2024). "In summary, this study found that MAP4K4 and WT1 contributed to SOX6‐induced cellular senescence in cervical cancer by synergistically activating the ATF2–TGFβ2–Smad2/3 signaling pathway." (PMID 38383842, 2024). "Senolytics can be used to enhance sensitivity to cisplatin treatment by inducing apoptosis of the SOX6‐induced senescent cervical cancer cells." (PMID 38383842, 2024). "The SOX6‐induced senescence of cervical cancer cells contributes to resistance to cisplatin treatment." (PMID 38383842, 2024). "ABT‐263 (navitoclax) and ABT‐199 (venetoclax), two classic senolytics, can specifically eliminate the SOX6‐induced senescent cervical cancer cells, and thus significantly improve the chemosensitivity of cisplatin‐resistant cervical cancer cells." (PMID 38383842, 2024). "MAP4K4 and WT1 contribute to SOX6‐induced cellular senescence in cervical cancer by synergistically activating the ATF2–TGFβ2–Smad2/3 signaling pathway." (PMID 38383842, 2024). "Mitogen-activated protein kinase kinase kinase kinase-4 (MAP4K4) was responsible for mediating the SOX6-induced autophagy, resulting in reduced chemosensitivity in cervical cancer." (PMID 38062424, 2023). "Inhibition of SOX6 greatly lightened the capabilities of cell proliferation, metastasis and chemoresistance in cervical cancer." (PMID 38062424, 2023). "First, we found that SOX6 promotes autophagosome formation and autophagic flux in cervical cancer cells, depending on its HMG domain." (PMID 40396003, 2022). "Next, we further investigated how to increase the chemosensitivity of cervical cancer cells to cisplatin, based on the existing compounds targeting the pathways of SOX6-induced autophagy." (PMID 40396003, 2022). "In contrast, SOX6 is known to function in tumor suppression of several cancers, including cervical cancer." (PMID 35418160, 2022). "Accordingly, these results suggest that the chemosensitivity of cervical cancer cells to cisplatin can be increased by inhibiting SOX6-induced autophagy." (PMID 40396003, 2022). "In this autophagy punctum, we discuss our recent findings about the mechanism of SOX6-induced autophagy and its potential significance in the platinum-based chemotherapy of cervical cancer." (PMID 40396003, 2022). "The result revealed that the SOX6-induced autophagy can reduce the chemosensitivity of cervical cancer cells to cisplatin in vitro and in vivo." (PMID 40396003, 2022). "miR-499a down-regulated SRY-box transcription factor 6 (SOX6), resulting in chemoresistance in cervical cancer calls." (PMID 34502361, 2021). "Accordingly, this study aims to investigate the mechanism of SOX6-induced autophagy and its potential significance in the platinum-based chemotherapy of cervical cancer." (PMID 34930918, 2021).
cervical cancer (continued). "Based on the fact that the level of endogenous SOX6 in CaSki cells was far lower than that in HeLa and SiHa cells, CaSki cells were also chosen to further explore the effect of SOX6 in autophagy of cervical cancer cells." (PMID 34930918, 2021). "SOX6 inhibits proliferation of cervical cancer cells by inducing cellular senescence." (PMID 39859532, 2025). "Notably, SOX6 has been shown to exert a influence in cervical cancer, breast cancer, and gastric cancer, while our study revealed that SOX6 levels decreased with diminishing PARP9 expression." (PMID 39739965, 2024). "Furthermore, SOX6 showed a significant involvement in tumor chemotherapy resistance in cervical cancer." (PMID 38062424, 2023). "Moreover, the role of SOX6-induced autophagy was explored in cervical cancer patients who underwent neoadjuvant chemotherapy, that is, the routine platinum-based chemotherapy." (PMID 40396003, 2022). "Because MAP4K4 is upstream in the pathway mediating SOX6-induced autophagy, so its inhibitor may be more specific in increasing the sensitivity of cervical cancer cells to cisplatin chemotherapy." (PMID 40396003, 2022). "Taken together, cisplatin can promote the expression of endogenous SOX6 and subsequently SOX6-mediated autophagy in cervical cancer cells, which may in turn reduce the chemosensitivity of cervical cancer cells to cisplatin." (PMID 40396003, 2022). "We previously found that Sex-determining region of Y-related high-mobility-group box 6 (SOX6), a tumor suppressor gene or oncogene in several cancers, could induce autophagy in cervical cancer." (PMID 34930918, 2021). "Firstly, we found that SOX6 could promote autophagy in cervical cancer cells depending on its HMG domain." (PMID 34930918, 2021). "Taken together, the sensitivity of cervical cancer cells to cisplatin could be increased by inhibiting the SOX6-induced autophagy through both autophagy and MAP4K4 inhibitors." (PMID 34930918, 2021). "Finally, we further investigated how to increase the sensitivity of cervical cancer cells to cisplatin based on the existing compounds targeting the pathways of SOX6-induced autophagy." (PMID 34930918, 2021). "Since MAP4K4 was at the upstream of SOX6-induced autophagy, its inhibitor might be more specific in inhibiting autophagy and subsequently increasing the sensitivity of cervical cancer cells to cisplatin chemotherapy." (PMID 34930918, 2021). "In line with this possibility, the sensitivity of HeLa cells to cisplatin was increased when the endogenous SOX6 was knocked out, thus the level of SOX6 might be able to predict the efficacy of cisplatin chemotherapy to cervical cancer cells." (PMID 34930918, 2021). "In this study, we found that SOX6 could induce autophagy in cervical cancer cells, and mitogen-activated protein kinase kinase kinase kinase-4 (MAP4K4) gene was identified as a direct target gene of SOX6." (PMID 34930918, 2021). "Moreover, the role of SOX6-induced autophagy was explored in cervical cancer patients who underwent routine neoadjuvant chemotherapy." (PMID 34930918, 2021).